MET (MET proto-oncogene, receptor tyrosine kinase)
Diseases named in the same sentence as MET in open-access papers (continued):
Sharing a sentence is not in itself a finding about the gene and the disease.
prostate carcinoma (150 papers, 2009 to 2026). A carcinoma that arises from epithelial cells of the prostate gland. "In line with this, classical MET expression has been associated with androgen-resistant prostate cancer tumors." (PMID 37370859, 2023). "In prostate cancer mouse model, the therapeutic efficiency of Cabozantinib appears to be strongly associated with MET pathway, reducing cancer cell invasion, and this action synergizes with androgen receptor antagonist therapy." (PMID 34745989, 2021). "This Hepsin activity is likely to be important for prostate cancer progression, because HGF/MET signaling pathway is strongly implicated in tumor progression and metastasis in prostate cancer." (PMID 24657880, 2014). "The data demonstrate that c-MET expression is abundant in prostate cancer but lacks a clear association with an unfavorable phenotype or a poor clinical outcome." (PMID 23251249, 2013). "This may also be due to the fact that MET mutations tended to be more common in prostate cancer (15.6%) than in breast (8.7%) and gynecological cancer (6.5%), although the number of cases of each was small." (PMID 34677235, 2021). "As decreased expression of the miR-34a targets, MET and Axl is associated with the induction of autophagy, understanding the form of autophagy induced by miR-34a in prostate cancer is important for therapeutic opportunities for miR-34a replacement in bone metastatic prostate cancer." (PMID 26313360, 2015). "Using the PC3M and PC3 hormone‐independent prostate cancer cell lines, we explored the regulatory interaction between MET signalling and ETV1/ERG activity and demonstrated a reciprocal action link." (PMID 39374163, 2025). "ETV1 and ERG fusions are present throughout the progression of prostate cancer, while MET, whose expression is repressed by the androgen receptor, appears mainly in advanced PCa and bone metastasis." (PMID 39374163, 2025). "MET is a potent oncogene down‐regulated by AR in prostate cancer, which explains its prevalence in advanced stages and bone metastases." (PMID 39374163, 2025). "To investigate the interplay between ETV1, ERG and MET signalling, we selected prostate cancer cell lines expressing MET endogenously, the PC3M and PC3." (PMID 39374163, 2025). "HGF is abundantly expressed in the microenvironment of metastatic prostate cancer in the bone, and high HGF levels are often associated with metastatic PCa to bone, suggesting that HGF is a key component of regulating HGF/MET signaling in mCRPC." (PMID 40723207, 2025). "This complex activates MET signaling pathways, which in turn promote the invasive growth of prostate cancer cells around nerve fibers." (PMID 39769452, 2024). "IGF-1R, a receptor tyrosine kinase, promotes cancer development and metastasis by mediating ligand-independent activation of MET (receptor tyrosine kinase) in prostate cancer." (PMID 38342894, 2024). "Other CD44 isoforms, such as CD44v9 in prostate cancer cells, stabilize the androgen receptor (AR) through MET signaling." (PMID 39769452, 2024). "Conversely, FOXP2 silencing using shRNA caused decreases in phospho-MET and phospho-AKT levels in two prostate cancer cell lines, PC3 and LNCaP." (PMID 37668356, 2023). "(E) The correlation analysis of gene expression between FOXP2 and MET signalling members in our primary prostate tumors (n = 92) and two other human primary prostate cancer datasets (GSE54460, n = 100; Taylor, n = 162) by qPCR." (PMID 37668356, 2023). "Among these hits were inhibitors targeting signaling molecules and pathways known to be involved in lineage plasticity and prostate cancer therapy resistance, such as aurora kinase, c-MET, and mTOR/PI3K." (PMID 37228586, 2023). "The EGFR/ERBB4, MET and IGF-1R families of growth factor receptor have been implicated in prostate cancer." (PMID 35954439, 2022).
prostate carcinoma (continued). "Again, in line with data reported here, it has been recently shown that in cellular models of castration-resistant prostate cancer, MET inhibition enhances the efficacy of PARPi by suppressing the ATM/ATR and PI3K/AKT pathways." (PMID 35628590, 2022). "Our investigations have revealed a novel consequence of potent activation of AR by MeT in prostate cancer cells." (PMID 36923279, 2022). "To better understand the activity of MeT in prostate cancer cells, we undertook a series of molecular assays." (PMID 36923279, 2022). "Overexpression of ligands and/or receptors of ERBB and MET pathways has been reported in prostate cancer." (PMID 35954439, 2022). "High expression of c-MET was found in 83% of prostate cancer BMs, and inhibitors targeting this protein have been used in clinical trials at various stages." (PMID 36389722, 2022). "To investigate the response of prostate cancer cells to MeT, we first examined changes in cell growth." (PMID 36923279, 2022). "A consistent finding throughout our study was that MeT exhibited greater potency—in terms of prostate cancer cell growth inhibition, AR DNA binding and transcriptional activity and viral mimicry responses—than DHT." (PMID 36923279, 2022). "The same dose of DHT did not have a significant effect on the cell cycle, providing additional evidence that MeT is a more potent androgen in terms of prostate cancer cell growth suppression." (PMID 36923279, 2022). "By dissecting MeT-induced transcriptional changes, we uncovered a novel response of prostate cancer cells to potent androgen stimulation." (PMID 36923279, 2022). "MET is co-expressed with stem-like markers in the invasive cell front of prostate cancer, and MET signaling also promotes prostate tumorigenesis, invasiveness and migration." (PMID 35954439, 2022). "Here, by using a synthetic and highly potent androgen, MeT, we provide new insights into the consequences of hyperactivation of AR in prostate cancer." (PMID 36923279, 2022). "In our previous report we and our collaborators demonstrated that AKT is inhibited by MET inhibitor as a downstream target of MET in prostate cancer mouse model and cell lines." (PMID 30700325, 2019). "In the COMET-1 trial, 682 patients with castrate-resistant prostate cancer who progressed after docetaxel and androgen modulators (abiraterone and/or enzalutamide) were randomly assigned to either cabozantinib (MET inhibitor) or prednisone." (PMID 29866143, 2018). "Prostate cancer demonstrates higher c-MET expression as the disease progresses to more advanced stages and to a castration resistant state." (PMID 30083962, 2018). "Prostate cancer (PCa) bone metastasis is uniquely associated with osteoblastic bone lesions and treatment with cabozantinib, a VEGFR-2 and MET inhibitor, leads to a reduction in number and/or intensity of lesions on bone scans." (PMID 29088840, 2017). "To verify these results, we additionally analyzed MET in 25 whole sections of prostate cancer at radical prostatectomy containing various tumor growth patterns, which also proved MET protein negative despite positive internal controls." (PMID 27105539, 2016). "Further research is clearly needed to fully characterize the nature, extent and duration of the effect of cabozantinib on c-MET phosphorylation and/or signaling in prostate cancer in vivo." (PMID 26762579, 2016). "The aim of this study was to investigate MET on protein, DNA and RNA level in clinical prostate cancer at various stages of progression." (PMID 27105539, 2016).
prostate carcinoma (continued). "Expression of MET was analyzed in hormone-naive primary prostate cancers (N=481), lymph node (N=40) and bone (N=8) metastases, as well as HRPC (N=54) and bone metastases (N=15)." (PMID 27105539, 2016). "Activation of MET in prostate cancer cell line DU145 results in cell migration, invasion and the acquisition of a stem-like phenotype." (PMID 27105539, 2016). "In contrast, MET immunohistochemistry revealed expression in 20% up to 100% of tumor cells in 18/23 (78%) prostate cancer bone metastasis." (PMID 27105539, 2016). "Activation of the HGF/MET axis in prostate cancer cell lines resulted in migration and induced orthotopic tumor formation." (PMID 27105539, 2016). "Various in vitro and in vivo studies have shown the involvement of MET in development and metastasis of prostate cancer." (PMID 27105539, 2016). "Results of MET protein expression in clinical prostate cancer are variable due to use of different antibodies and staining techniques." (PMID 27105539, 2016). "While many groups have studied the role of HGF/MET signaling in epithelial-mesenchymal transition, little is known of the actual role of this pathway in clinical prostate cancer." (PMID 27105539, 2016). "Our objective was to investigate MET on protein, DNA and RNA level in clinical prostate cancer at various stages of progression." (PMID 27105539, 2016). "Future studies evaluating MET pathway inhibitors, particularly in prostate cancer and/or in combination therapies, are warranted." (PMID 26155941, 2015). "Gene ontology analysis of differentially expressed genes revealed that lack of Sost in the bone microenvironment up-regulated several genes associated with the GO term “chemotaxis” including MET, PDGFA, FER, NRP2, and EZR in prostate cancer." (PMID 27600237, 2015). "Tumor effects due to in prostate cancer, c-MET expression is elevated in bone metastases compared with lymph node metastases or primary tumors, and in tumors in castrated patients compared with non-castrated patients." (PMID 25277255, 2014). "In the present study, the frequency and the potential clinicopathological role of c-MET protein expression was investigated in prostate cancer." (PMID 23251249, 2013). "Recently published studies demonstrate the anti-proliferative efficacy of c-MET inhibitors in combination with androgen ablation therapy for advanced prostate cancer." (PMID 23251249, 2013). "They observed c-MET expression in 84% of cases and revealed an association between c-MET expression and advanced grade prostate cancers (P<0.001)." (PMID 23251249, 2013). "A total of 3,378 different prostate cancers were successfully analyzed for c-MET expression by immunohistochemistry and follow-up data were available for 4,104 patients." (PMID 23251249, 2013). "In conclusion, the results of this study reveal that c-MET is frequently overexpressed in prostate cancer." (PMID 23251249, 2013). "Recently, c-MET has been proposed as a candidate for targeted cancer therapy in prostate cancer and other tumors." (PMID 23251249, 2013). "To determine c-MET expression at the invasive front in prostate cancer, we compared the presence of high c-MET expressing cells at the perimeter and the centre of well-fixed RP specimens (N = 94)." (PMID 22110593, 2011). "Previously, we have demonstrated that c-MET is over-expressed in scattered prostate cancer cells at radical prostatectomies." (PMID 22110593, 2011). "In prostate cancer, c-MET is present at low levels, with a minority of cells displaying high protein expression." (PMID 22110593, 2011). "In conclusion, activation of the HGF/c-MET pathway gives rise to a stem-like phenotype, preferentially at the invasive front of human prostate cancer." (PMID 22110593, 2011). "These cells co-expressed CD49b and CD49f, indicating that c-MET positive cells indeed co-express a stem-like cell phenotype in human prostate cancer." (PMID 22110593, 2011).
prostate carcinoma (continued). "In conclusion, activation of c-MET in prostate cancer cells induced a stem-like phenotype, indicating a dynamic relation between differentiated and stem-like cells in this malignancy." (PMID 22110593, 2011). "Our objective is to determine the role of immature cells in prostate cancer by analysis of the HGF/c-MET pathway." (PMID 22110593, 2011). "In this study, we demonstrate that activation of c-MET leads to induction of a stem-like phenotype in prostate cancer." (PMID 22110593, 2011). "To explore the molecular pathways relevant for c-MET function in prostate cancer, we performed microarray expression analysis of DU145 cells stimulated with HGF." (PMID 22110593, 2011). "Little is known on the role of c-MET in relation to stem-like cells in prostate cancer and how in vitro studies on stem-like cells translate to actual cancer in patients." (PMID 22110593, 2011). "In this study, we demonstrate that high c-MET expressing cells preferentially occur at the periphery of prostate cancer and in areas of extra-prostatic extension." (PMID 22110593, 2011). "Despite the limited availability of c-MET models in prostate cancer, these results indicate that HGF-mediated induction of a stem-like phenotype is representative for human disease." (PMID 22110593, 2011). "Inhibition of c-MET has potency in blocking stem-like cell transition and therefore is a promising tool for targeted therapy of prostate cancer." (PMID 22110593, 2011). "Previously, others and we have shown that c-MET and basal cell marker Keratin 5 are co-expressed within the same cell population in prostate cancer." (PMID 22110593, 2011). "MET signalling and ETS gene fusions are intimately linked to high‐grade prostate cancer." (PMID 39374163, 2025). "Thus, our results suggest that the collective influence of ETV1/ERG and MET signalling can have a significant impact on the trajectory of prostate cancer progression, precipitating its ascent to high‐grade malignancy." (PMID 39374163, 2025). "The integrin acts upstream of MET in an HGF-independent manner such that treating or plating ovarian, breast, lung or prostate cancer cells with or on integrin substrates, such as fibronectin, collagen or laminin, triggers MET phosphorylation in various cell models." (PMID 40138447, 2025). "Importantly, loss of AR resulted in an enhanced expression of PAX6, which reprogramed the lineage plasticity of prostate cancer cells to develop NE phenotypes through the MET/STAT5A signaling pathway." (PMID 38745318, 2024). "By activating FYN, HGF/MET promotes the progression of prostate cancer." (PMID 36740671, 2023). "Despite these encouraging perspectives, the multiple crosstalk between EGFR, IGF-1R and MET signaling highlighted in preclinical and clinical studies, and herein assessed in castration-tolerant prostate cancer cells, call for concomitant targeting of these three receptors." (PMID 35954439, 2022). "An important question that still needs to be addressed is whether, and to what extent, activation of IFN signaling contributes to MeT-mediated suppression of prostate cancer cell growth." (PMID 36923279, 2022). "GJB2, MET, MUTYH and VHL mutations ranked top in kidney cancers, and ATM and CHEK2 mutations ranked top for bladder cancer, while ATM and BRCA1 mutations ranked top for prostate cancer." (PMID 36451132, 2022). "Additionally, as in the KAI1 re‐expressing PC3 prostate cancer cells that showed a suppression of both integrin‐ and ligand‐mediated activation of c‐Met,60 the expression of phospho‐c‐MET was also decreased in the KDIP‐injected metastatic liver nodules." (PMID 35853101, 2022). "Another PRR involved in antiviral responses, STING, is best known for its role in sensing of cytosolic DNA but also serves as a detector of RNA viruses and can interact with RIG-I: similarly to RIG-I, STING was strongly upregulated by MeT in prostate cancer cells." (PMID 36923279, 2022).
prostate carcinoma (continued). "Given its potent growth-inhibitory activity, we hypothesized that further dissecting the MeT-regulated transcriptome of MeT could yield new mechanistic insights into AR's tumor suppressive activity in prostate cancer." (PMID 36923279, 2022). "Moreover, the overexpression of exogenous MET in prostate cancer cell lines LNCaP and 22RV1 resulted in drug resistance." (PMID 34761497, 2021). "Moreover, p63 cell survival promoting capabilities engage the actions of FASN and inhibition of FASN induces endoplasmic reticulum stress in prostate cancer cells as well as down-regulates c-MET expression." (PMID 33572160, 2021). "Interestingly, FYN has been shown to be an important effector in the HGF/MET signaling axis that acts as a crucial oncoprotein in prostate cancer metastasis." (PMID 32811808, 2020). "In order to determine whether individual patients could be stratified for therapy, it is important to gain insight in MET protein expression in prostate cancer." (PMID 27105539, 2016). "Analysis of MET protein expression and genetic alterations might contribute to therapeutic stratification of prostate cancer patients." (PMID 27105539, 2016). "As the receptor for HGF, c-MET, has been shown to be upregulated in androgen-insensitive and metastatic prostate cancer cells, it would be interesting in future work to test whether this is linked to increased invasiveness via EphA receptor-mediated CIL." (PMID 24795148, 2014). "Another group examined 108 prostate cancers and observed c-MET expression in 45% of cases." (PMID 23251249, 2013). "This illustrates that co-targeting of c-MET and androgen signaling pathway might be a therapeutic option for the treatment of prostate cancer in the future." (PMID 23251249, 2013). "However, the frequent presence of high levels of membranous c-MET protein in prostate cancer cells makes c-MET an attractive target for imaging and treatment." (PMID 23251249, 2013). "Here, we show, using cell models of advanced prostate cancer, that ETS translocation variant 1 (ETV1) and transcriptional regulator ERG (ERG) transcription factors (members of the ETS family) promote tumour properties, and that activation of MET signalling enhances these effects." (PMID 39374163, 2025). "In support of this, we demonstrated that MeT enhanced the immunogenicity of murine prostate cancer cells leading to elevated T-cell responses in a coculture system, providing in vitro evidence that a viral mimicry response induced by this androgen could modulate the tumor immune microenvironment." (PMID 36923279, 2022). "Furthermore, we conducted the overexpression of exogenous MET in prostate cancer cell lines LNCaP and 22RV1 to reach olaparib‐resistance states, and following treatment with olaparib or crizotinib alone or a combination of the two, then detected the expression of PI3K/AKT by western blot." (PMID 34761497, 2021). "Thus, miR-34a's effects on autophagy may differ depending on the conditions by which autophagy is induced and downregulation of different targets in different tissues (such as MET and Axl in prostate cancer cells)." (PMID 26313360, 2015). "After determining that HGF is exogenously supplied to prostate cancer cells, the following experiments were performed to determine the impact of HGF/MET activity on the proliferation and phosphorylation of MET and STMN1." (PMID 40723207, 2025). "In this study, by using cellular models of advanced prostate cancer, we undertake an investigation of ETV1/ERG transcription factors and MET signalling interplay in tumour progression mechanic." (PMID 39374163, 2025). "In our study, we found a positive correlation between the expression of both MET and HGF and the expression of FOXP2 in prostate cancer tissues, FOXP2-overexpressing human prostate epithelial cells RWPE-1, and FOXP2-overexpressing NIH3T3 cells." (PMID 37668356, 2023).